TRIM11 (tripartite motif containing 11)
Description:
E3 ubiquitin-protein ligase that promotes the degradation of insoluble ubiquitinated proteins, including insoluble PAX6, poly-Gln repeat expanded HTT and poly-Ala repeat expanded ARX (By similarity). Mediates PAX6 ubiquitination leading to proteasomal degradation, thereby modulating cortical neurogenesis (By similarity). May also inhibit PAX6 transcriptional activity, possibly in part by preventing the binding of PAX6 to its consensus sequences (By similarity). May contribute to the regulation of the intracellular level of HN (humanin) or HN-containing proteins through the proteasomal degradation pathway (By similarity). Mediates MED15 ubiquitination leading to proteasomal degradation. May contribute to the innate restriction of retroviruses. Upon overexpression, reduces HIV-1 and murine leukemia virus infectivity, by suppressing viral gene expression. Antiviral activity depends on a functional E3 ubiquitin-protein ligase domain. May regulate TRIM5 turnover via the proteasome pathway, thus counteracting the TRIM5-mediated cross-species restriction of retroviral infection at early stages of the retroviral life cycle. Acts as an inhibitor of the AIM2 inflammasome by promoting autophagy-dependent degradation of AIM2. Mechanistically, undergoes autoubiquitination upon DNA stimulation, promoting interaction with AIM2 and SQSTM1/p62, leading to AIM2 recruitment to autophagosomes.
Synonyms: RNF92; BIA1
Tractability: PROTAC: UniProt records ubiquitination sites on it; ubiquitination databases record sites on it; its protein half-life has been measured.
Gene: Protein-coding gene on chromosome 1 (228,393,672 to 228,406,841, reverse strand). Ensembl gene ENSG00000154370.
Subcellular location: Cytoplasm; Nucleus
Subcellular location (Human Protein Atlas): Cytosol; Nucleoplasm
Pathways (Reactome):
Immune System: Antigen processing: Ubiquitination & Proteasome degradation
Gene Ontology:
Molecular function: protein binding; protein-macromolecule adaptor activity; ubiquitin protein ligase activity; ubiquitin-protein transferase activity; protein domain specific binding; zinc ion binding
Biological process: antiviral innate immune response; host-mediated suppression of symbiont invasion; negative regulation of AIM2 inflammasome complex assembly; protein autoubiquitination; protein ubiquitination; suppression of viral release by host; negative regulation of viral transcription; regulation of gene expression; negative regulation of DNA-templated transcription; negative regulation of neurogenesis; positive regulation of viral entry into host cell
Cellular component: cytoplasm; cytosol; nucleoplasm; nucleus
Genetic constraint (gnomAD): Loss-of-function variants: 15 observed, 25.96 expected, observed/expected ratio (o/e) 0.58, 90% interval 0.39 to 0.89. The upper end of that interval is the gene's LOEUF score, 0.89, which puts it in group 3 of 6, group 1 being the genes least tolerant of losing a copy. Missense variants: 499 observed, 571.93 expected, observed/expected ratio (o/e) 0.87, 90% interval 0.81 to 0.94. Synonymous variants: 281 observed, 258.82 expected, observed/expected ratio (o/e) 1.09, 90% interval 0.98 to 1.2.
Homologues: Orthologues: chimpanzee TRIM11 (100% identical), macaque TRIM11 (99% identical), pig TRIM11 (91% identical), rat Trim11 (90% identical), guinea pig TRIM11 (90% identical), mouse Trim11 (90% identical), dog TRIM11 (89% identical), rabbit TRIM11 (66% identical). Paralogues in human: TRIM17 (47% identical), TRIM58 (43% identical), TRIM39 (42% identical), TRIM27 (40% identical), TRIM41 (39% identical), TRIM21 (38% identical), TRIM4 (37% identical), TRIML1 (36% identical), TRIM7 (34% identical), TRIM68 (33% identical), TRIM38 (33% identical), TRIM26 (33% identical), and 68 more.
Diseases named in the same sentence as TRIM11 in open-access papers:
TRIM11 is named in the same sentence as 58 diseases in open-access papers, as found by Europe PMC text mining. Sharing a sentence is not in itself a finding about the gene and the disease. The quoted sentences say what the papers report.
breast carcinoma (13 papers, 2018 to 2024). "This study further revealed that TRIM11 knockdown suppressed breast cancer cell proliferation and migration and that TRIM11 deficiency in animal models increased the KDM5C level and suppressed breast tumor growth." (PMID 39394462, 2024). "Previous studies have shown that TRIM11 is upregulated and associated with tumor growth and metastasis in glioma, lung cancer, hepatocellular cancer, and breast cancer." (PMID 35237324, 2022). "TRIM11 upregulation is also associated with increased motility, invasiveness, and cell proliferation of lung and breast cancer cells and glioblastoma cell lines." (PMID 34943200, 2021). "Collectively, these findings indicate that KDM5C degradation via TRIM11 promotes breast cancer cell proliferation and migration." (PMID 39394462, 2024). "In conclusion, our investigation illustrated that SOX13 facilitated breast cancer cell proliferation and glycolysis by modulating Wnt/β-catenin signaling pathway affected via TRIM11." (PMID 35611828, 2022). "In the present study, we systemically summarized that SOX13 promoted glycolysis and viability of breast cancer cells by activating TRIM11-mediated Wnt/β-catenin signaling pathway." (PMID 35611828, 2022). "Our IHC study of breast cancer patient tissues show that in breast cancers, TRIM11 is mainly located in nuclei." (PMID 36192394, 2022). "In breast cancer, TRIM11 is involved in the regulation of multiple processes, including immune response, migration-related pathway and lipid metabolism." (PMID 36192394, 2022). "In breast cancer patient tissues, TRIM11 is highly expressed and KDM5C is lower expressed, and their expression is negatively correlated." (PMID 36192394, 2022). "Our data show that KDM5C is also involved in the regulation of inflammation genes, which suggest that TRIM11-mediated KDM5C degradation is probably also involved in the immune response in breast cancer." (PMID 36192394, 2022). "Our study demonstrates that TRIM11 promotes breast cancer through targeting KDM5C and reprogramming epigenetic modifications on enhancers." (PMID 36192394, 2022). "TRIM11 interacts with KDM5C, catalyzes K48-linked ubiquitin chain on KDM5C and regulates KDM5C stability in breast cancer cells." (PMID 36192394, 2022). "We found that TRIM11 knockdown elevated KDM5C protein level in breast cancer cell lines MDA-MB-231, MDA-MB-468, and kidney cell lines HEK293T, but did not affect its mRNA level." (PMID 36192394, 2022). "In conclusion, this study for the first time revealed that SOX13 promoted breast cancer progression by accelerating TRIM11/Wnt/β-catenin network-mediated glycolysis." (PMID 35611828, 2022). "TRIM11 was proved to be closely related with breast cancer, and SOX13 was proved to affect various cancers by regulating Wnt/β-catenin pathway." (PMID 35611828, 2022). "In the breast cancer tissues of Trim11+/+ and Trim+/− mice, MCAM expression was down-regulated with Trim11 deficiency." (PMID 36192394, 2022). "We established stable expression cell lines of HA-KDM5C and HA-TRIM11 in MDA-MB-231 breast cancer cells, and verified the function of exogenous expressed TRIM11 on down-regulating KDM5C." (PMID 36192394, 2022). "High TRIM11 expression was also recognized as an independent marker of poor prognosis in patients with breast cancer, colon and prostate adenocarcinoma, lung NSCC, HCC, and glioblastoma and it has also been correlated with advanced disease stage." (PMID 34943200, 2021). "After downregulating the expression of TRIM11 in breast cancer cells, improved therapeutic effects can be achieved by inhibiting the ERK1/2 and JNK1/2 signaling pathways." (PMID 33173411, 2020). "Recently, TRIM11 promotes proliferation and glycolysis of breast cancer cells via targeting the AKT/GLUT1 pathway." (PMID 32051827, 2020). "Subsequently, TRIM11 was also shown to exert an oncogenic role in lung cancer, liver cancer, breast cancer, and ovarian cancer via various mechanisms." (PMID 32382014, 2020).
breast carcinoma (continued). "We observed similar effects of TRIM11 knockdown in human breast cancer MCF7 cells and osteosarcoma U2OS cells." (PMID 29581427, 2018). "Nevertheless, whether TRIM11 regulates Wnt/β-catenin signaling pathway in breast cancer progression remains unclear." (PMID 35611828, 2022). "Analysis with public data showed that TRIM11 was highly expressed in breast cancer, as well as in many other types of cancer, compared with their corresponding normal tissues, and the patients with higher TRIM11 expression is associated with worse survival rates." (PMID 36192394, 2022). "These suggest that in breast cancer tissues, TRIM11 probably mainly regulates KDM5C in nuclei." (PMID 36192394, 2022). "Therefore, we assumed that SOX13 affected breast cancer and glycolysis by mediating TRIM11/Wnt/β-catenin pathway." (PMID 35611828, 2022). "Previously, TRIM11 upregulation had been detected in a series of human cancers, such as pancreatic ductal adenocarcinoma, renal clear cell carcinoma, ovarian cancer, and breast cancer." (PMID 35237324, 2022). "TRIM11 and KDM5C stable knockdown cell lines were also established in MDA-MB-468 and ZR-75-30 breast cancer cells." (PMID 36192394, 2022). "Our data show that TRIM11 and KDM5C regulate the expression of MCAM in breast cancer cells, through targeting an enhancer close to MCAM TSS." (PMID 36192394, 2022). "TRIM11 regulates proliferation and migration of breast cancer cells through KDM5C, and TRIM11 promotes breast cancer and regulates KDM5C stability in an in vivo animal model." (PMID 36192394, 2022). "To further investigate the molecular mechanisms for TRIM11 and KDM5C in regulating breast cancer, we performed RNA-Seq and ChIP-Seq analysis in TRIM11 or KDM5C knockdown cells derived from MDA-MB-231." (PMID 36192394, 2022). "Analysis of patient survival rate with TCGA breast cancer data show that patients with higher MCAM expression have worse survival rate, further supporting that regulation of MCAM by TRIM11 and KDM5C is important for breast cancer." (PMID 36192394, 2022). "We divided the tissues into four subgroups according to the provided information of molecular marks, and found that TRIM11 was higher expressed and KDM5C was lower expressed in all four groups of breast cancer tissues." (PMID 36192394, 2022). "To further explore the relationship between TRIM11 and KDM5C in breast cancer patient tissues, we performed immunohistochemical (IHC) staining with commercially available breast cancer tissue arrays." (PMID 36192394, 2022). "All these indicated that TRIM11 plays an oncogenic role in breast cancer animal model and regulates KDM5C in breast cancer tissues." (PMID 36192394, 2022). "In breast cancer, KDM5C acts as a tumor suppressor through regulating enhancer function, which is targeted by an oncogenic ubiquitin E3 ligase, tripartite motif containing 11 (TRIM11)." (PMID 38012744, 2023). "The results suggest that TRIM11 selectively regulates KDM5C stability in breast cancer cells and HEK293T, but not other tested cell lines." (PMID 36192394, 2022). "These suggest that TRIM11 plays oncogenic roles in many types of cancer, while KDM5C may be behaves as a tumor suppressor only in breast cancer." (PMID 36192394, 2022).
nasopharyngeal carcinoma (11 papers, 2020 to 2024). A carcinoma arising from the nasopharyngeal epithelium. "TRIM11, which has been linked to the migration and invasion of nasopharyngeal carcinoma, was found to be upregulated in NSCLC patients at both the mRNA and protein levels." (PMID 37604203, 2023). "In nasopharyngeal carcinoma, TRIM11 is upregulated by a METTL3-mediated m6A modification that regulates β-catenin signaling to promote cisplatin resistance." (PMID 39199429, 2024). "Although tripartite motif-containing protein 11 (TRIM11) is known to be associated with a variety of cancers, its role in nasopharyngeal carcinoma (NPC) is unclear." (PMID 36376537, 2023). "In a similar vein, Wnt/β-catenin signalling is implicated in the development of chemoresistance and has been shown to be modulated by m6A modification via the upregulation of TRIM11 in nasopharyngeal carcinoma." (PMID 37444417, 2023). "Methylated RNA immunoprecipitation (Me-RIP) study suggests that TRIM11 m6A level was higher in cisplatin resistant cells compared to sensitive cells in nasopharyngeal carcinoma (NPC) lines." (PMID 33718113, 2020). "For example, in nasopharyngeal carcinoma (NPC), TRIM11 is upregulated by METTL3-mediated m6A modification, which modulates β-catenin signaling, thus promoting cisplatin resistance." (PMID 36960074, 2023). "In nasopharyngeal carcinoma (NPC), METTL3 has been shown to induce high m6A enrichment in TRIM11, a tripartite motif-containing protein family member that positively modulates β-catenin signaling, to promote cisplatin resistance." (PMID 34315512, 2021). "Upregulation of TRIM11 can further activate the β-catenin/ABCC9 axis, which promotes resistance to chemotherapy in nasopharyngeal carcinoma." (PMID 34858499, 2021). "In drug-resistant nasopharyngeal carcinoma cells, the m6A modification of TRIM11 mediated by METTL3 promotes the stability of TRIM11 mRNA through the m6A-IGF2BP2-dependent pathway, which partially increases the expression of the TRIM11 protein." (PMID 34858499, 2021). "In nasopharyngeal carcinoma (NPC), METTL3-mediated m6A modification was enriched in TRIM11 mRNA and stabilized it depending on IGF2BP2." (PMID 36810281, 2023).
lung cancer (8 papers, 2016 to 2023). A malignant neoplasm involving the lung. "In lung cancer, TRIM11 is reported to promote cell proliferation and invasion via activating the PI3K/AJT pathway." (PMID 33613102, 2021). "The oncogenic function of TRIM11 has been investigated in different types of human cancers, including hepatocellular carcinoma cancer, lung cancer, and glioma 27-30." (PMID 33613102, 2021). "Overexpression of TRIM11 promotes the growth and metastasis of lung cancer, glioma cells, hepatocellular carcinoma cells, osteosarcoma cells, and ovarian cancer cells." (PMID 33173411, 2020). "Later, overexpression of TRIM11 was found in high-grade gliomas, lung cancer, liver and pancreatic cancer with an oncogenic function promoting cell growth, migration, invasion and chemoresistance, suggesting TRIM11 as a novel target for tumour treatment." (PMID 30974870, 2019). "TRIM11 is also highly expressed in lung cancer tissues and cell lines, and higher expression of TRIM11 is correlated with the poorer prognosis in lung cancer patients." (PMID 27888625, 2016). "TRIM11 (tripartite motif-containing protein 11) is an E3 ubiquitin ligase recently identified as an oncogene in malignant glioma and lung cancer." (PMID 27888625, 2016). "TRIM11 expression is upregulated, and it functions as an oncogenic protein in malignant gliomas and lung cancer." (PMID 27888625, 2016). "ERK and PI3K/AKT pathways can promote tumor cell growth and metastasis and a notable decrease of ERK and PI3K/AKT activation can be found in TRIM11 knocked down lung cancer cells." (PMID 27456341, 2016). "The effect of TRIM11 in promoting the EMT process has been confirmed in hepatocellular cancer, gastric cancer, and lung cancer." (PMID 36261847, 2022). "The oncogenic functions of TRIM11 in cancer have been investigated in cholangiocarcinoma, HCC, lung cancer, ovarian cancer, and cervical cancer." (PMID 36261847, 2022).
glioma (7 papers, 2019 to 2024). A benign or malignant brain and spinal cord tumor that arises from glial cells (astrocytes, oligodendrocytes, ependymal cells). "Knockdown of TRIM11 inhibited glioma cell proliferation, migration, and invasion, whereas low levels of TRIM11 resulted in downregulation of EGFR, p-c-Raf, p-MEK1/2, and p-44/42MAPK." (PMID 36139694, 2022). "TRIM11 has been suggested as a poor prognostic marker in gliomas, since HGG patients with lower levels of TRIM11 exhibited prolonged survival compared to those with a higher TRIM11 expression." (PMID 36139694, 2022). "In addition to being overexpressed in gliomas, knockdown of TRIM11 in primary glioma cultures was sufficient to significantly reduce levels of EGFR." (PMID 33432111, 2021). "Tripartite motif-containing protein 11 (TRIM11), overexpressed in glioma, promotes proliferation, invasion, migration, and glial tumor growth via the induction of EGFR." (PMID 35832194, 2022). "One of the early studies identified TRIM11 as being upregulated in high-grade gliomas (HGG) and glioma-derived stem-like cells (GSCs), leading to a more aggressive glioma phenotype." (PMID 36139694, 2022). "Furthermore, overexpression experiments suggest that TRIM11 exerts its oncogenic function in gliomas via EGFR/MAPK signaling and most likely without involvement of the PI3K/Akt pathway." (PMID 36139694, 2022).
hepatocellular carcinoma (7 papers, 2019 to 2024). A malignant tumor that arises from hepatocytes. "It has been demonstrated that TRIM11 upregulation contributes to the growth and metastasis of hepatocellular cancer cells as well as ovarian cancer cells." (PMID 31950060, 2019). "Increased TRIM11 mRNA expression-compared to normal tissue- has been described in hepatocellular carcinoma, which translated to increased protein expression by IHC, lung non-small cell carcinoma (NSCC), prostatic, colonic, gastric adenocarcinomas, and lymphoma." (PMID 34943200, 2021). "In hepatocellular carcinoma (HCC), enforced expression of TRIM11 promotes cell proliferation, invasion, and migration by activating of the PI3K/Akt signaling pathway." (PMID 31820796, 2019).
Alzheimer disease (6 papers, 2005 to 2026). A progressive, neurodegenerative disease characterized by loss of function and death of nerve cells in several areas of the brain leading to loss of cognitive function such as memory and language. "TRIM11 interacts with Humanin, a protein that suppresses the neurotoxicity associated with Alzheimer's disease." (PMID 16098226, 2005). "A reduction in TRIM11 protein levels has been reported in Alzheimer's disease (AD) brains, and TRIM11 has been suggested to play a role in the SUMOylation of mutant tau as well as excess normal tau and its subsequent degradation by proteasomes." (PMID 38348509, 2024). "For example, downregulation of TRIM11 contributes to the pathogenesis of tau protein diseases, and restoration of TRIM11 expression may be an effective therapeutic strategy for Alzheimer’s disease." (PMID 38731834, 2024). "However, according to bioinformatics gene data from TargetScan, miR-5193 was predicted to target TRIM11 and early published studies have identified TRIM11 involvement in neurodegenerative disorders as well as in the regulation of Alzheimer’s disease by destabilizing intracellular humanin." (PMID 38882525, 2024).